RNU6-1052P (RNA, U6 small nuclear 1052, pseudogene)
Gene: Small nuclear RNA gene on chromosome 7 (56,402,070 to 56,402,173, reverse strand). Ensembl gene ENSG00000223330.
Homologues: Orthologues: chimpanzee U6 (100% identical), macaque U6 (91% identical), pig U6 (82% identical), pig U6 (78% identical), dog U6 (77% identical). Paralogues in human: RNU6-719P (99% identical), RNU6-1319P (97% identical), RNU6-241P (97% identical), RNU6-747P (97% identical), RNU6-1076P (96% identical), RNU6-1100P (96% identical), RNU6-1118P (96% identical), RNU6-1217P (96% identical), RNU6-355P (96% identical), RNU6-447P (96% identical), RNU6-785P (96% identical), RNU6-791P (96% identical), and 1285 more.